MYC (MYC proto-oncogene, bHLH transcription factor)
Diseases named in the same sentence as MYC in open-access papers (continued):
Sharing a sentence is not in itself a finding about the gene and the disease.
breast cancer (continued). "Breast cancer cells, after MYC/KRAS- or MYC/ERBB2- ablation, are similar to glioma cells in their acquired resistance to phosphoinositol-3-kinase (PIK3) inhibitors." (PMID 32300553, 2020). "We found that the promoter regions of PSAT1 and PHGDH contain binding sites for MYC-controlled activating transcription factor 4 (ATF4), which was reported to regulate PSAT1 expression in breast cancer." (PMID 32138178, 2020). "Co‐amplified MYC and PVT1 genes have been identified as candidate oncogenes in ER‐positive, HER2‐positive breast cancers." (PMID 32058674, 2020). "Expected staining patterns were demonstrated in the human positive control tissues: seminoma for OCT4 and NANOG, normal skin for SOX2, breast carcinoma for KLF4, and normal colon for c-MYC." (PMID 32019273, 2020). "The levels of the MYC proto‐oncogene (MYC) and cyclin D1 (CCND1) were detected by western blotting and quantitative reverse transcription‐polymerase chain reaction in breast cancer cells with SIRT4 overexpression or depletion." (PMID 31573734, 2019). "It has been proven that c-MYC transforms human mammary epithelial cells through the repression of the Wnt inhibitors DKK1 and SFRP1 in breast cancer cell lines." (PMID 30866868, 2019). "MYC is a member of OSKM acting on cell reprogramming and is also a frequently deregulated oncogene in breast cancers, particularly in the basal-like subtype." (PMID 31013830, 2019). "Overexpression of WT1 induces a significant increase in the abundance of endogenous MYC protein in breast cancer cells, whereas a WT1/BASP1 complex represses the MYC promoter." (PMID 31058089, 2019). "For example, MDM4 and EGFR were enriched in glioblastoma, MYC and ERBB2 were enriched in breast cancer whereas MDM2 was enriched in both." (PMID 30674876, 2019). "It should be noted that some genes highly related with breast cancer rank at top but are missed by the NCG4.0 such as the CREBBP, RHOA, HDAC1, ATM and MYC." (PMID 31088372, 2019). "To further experimentally verify the effect of circMYC on MYC protein expression, we overexpressed circMYC by transferring a synthetic circMYC expression vector into MDA-MB-231, a human breast cancer cell line." (PMID 31446897, 2019). "Howard Chang’s group recently showed that targeted CRISPR interference at the PVT1 promoter enhanced breast cancer cell competition and growth in vivo due to the competition between PVT1 and MYC for engagement with four intragenic enhancers in the PVT1 locus." (PMID 31127282, 2019). "MYC was found to repress the WNT inhibitors DKK1 and SFRP1, leading to the activation of the WNT pathway in breast cancer cell lines." (PMID 31623618, 2019). "The expression levels of cytosolic BCL-2 family proteins were defined as negative, weak, intermediate, or strong, and the results of both the MYC and the BCL-2 family stainings were analyzed across the major breast cancer subtypes." (PMID 30728358, 2019). "In breast cancer-initiating stem cells, when stimulated by VEGF, VEGFR2 binds to JAK2 and activates STAT3, and maintains cell self-renewal by promoting MYC and SOX2 expression and induces sphere formation." (PMID 30819137, 2019). "The MYC pathway, PD-L1 (CD274) and CD47 were elevated in TNBC, particularly in PTEN-low/miRNA-low TNBCs (group “a”), relative to HER2+ or ER+ breast cancer in most cohorts." (PMID 31836816, 2019). "In analogy, we identified MYC enrichment at the identical site in the CDK7 promoter in various ChIP-seq data sets from breast cancer and B-cell malignancies suggesting that both MITF and MYC are able to directly transactivate CDK7." (PMID 30651597, 2019).
breast cancer (continued). "This study focused on the role of SIRT4 in the tamoxifen sensitivity of breast cancer and demonstrated that SIRT4 blocks the transcription and translation of MYC and CCND1 in ER‐positive breast cancer, through the STAT3 pathway." (PMID 31573734, 2019). "We then proceeded to investigate MYC, ATR and ATM protein levels in clinical breast carcinoma samples." (PMID 30746633, 2019). "Compelling evidences are available about the crosstalk between c-MYC and VEGF-A and their positive role and overexpression in breast cancer progression." (PMID 30239898, 2018). "In this study, we found that MYC proto‐oncogene, bHLH transcription factor (MYC) and DNA methyltransferase 3A (DNMT3A) were highly expressed in TNBC tissues compared with other breast cancer subtypes, while miR‐200b expression was inhibited significantly." (PMID 30324719, 2018). "To further explore the function of MYC association with the NuA4 complex in cancer, we examined effects of shRNA-mediated knockdown of MYC and the Tip60 component of the NuA4 complex on gene expression in MD-MB231 human breast cancer cells." (PMID 30108681, 2018). "The locus, including the gene desert and its flanking genes, MYC, PVT1 and FAM84B, is also frequently amplified in human breast cancer." (PMID 30526553, 2018). "To establish the pathological relevance of the anti-correlation between MYC overexpression and ESR1/GATA3 downregulation, we assessed the expression level of these ML-specific TFs in large cohorts of breast cancer samples." (PMID 29523784, 2018). "On one hand, FOXP3 can inhibit breast cancer cell proliferation by regulating the expression of breast cancer oncogenes such as HER2, MYC and SKP216, 19–22." (PMID 29970908, 2018). "We examined the change in Shannon index, a mathematical diversity measure used in ecology, for c-MYC copy number variation (CNV) after neoadjuvant chemotherapy and evaluated its clinical significance in breast cancer." (PMID 30420657, 2018). "4T1 is a cell line derived from a spontaneous mammary tumor from BALB/c mouse and the MYC-HRAS MOSE are murine ovarian surface epithelial cells transformed by the introduction of mutant MYC and HRAS." (PMID 29348410, 2018). "Co-amplifications of other driver loci in breast cancer are observed, for example chr20:ZNF217 and chr8:MYC is seen in 18 samples (P = 1e−04) and chr20:ZNF217 and chr8:ZNF703 in 11 samples (P = 9e−03) (available at Annals of Oncology online)." (PMID 30252041, 2018). "The expressions of MYC and its downstream immune checkpoint genes (CD47 and PD-L1) in samples with TNBC and Her-2 positive breast cancer were detected by qRT-PCR." (PMID 29416769, 2018). "Treatment of breast cancer cells with the MYCMI-6, MYCMI-11 and MYCMI-14 for 24 hours significantly decreased MYC:MAX isPLA signals to 7%, 23% and 23% of DMSO-treated controls, respectively." (PMID 29968736, 2018). "To further understand gene regulation in cancer by MYC and the NuA4 complex, we performed RNA-seq analysis of MD-MB231 breast cancer cells following knockdown of MYC or Tip60 - the HAT enzyme of the NuA4 complex." (PMID 30108681, 2018). "Our study offers the CLK inhibitor as a novel therapeutic option for cancer patients, particularly for poor prognosis patients with MYC‐amplified and high CLK2‐expressing breast cancer." (PMID 29769258, 2018). "In this study, miR‐200b expression in TNBC tissues was inhibited compared with other breast cancer subtypes, while DNMT3A and MYC expression were elevated significantly." (PMID 30324719, 2018). "KRAS signaling and MYC targets v1 gene sets were de-emphasized in the BRCA + OV + UCEC model, pointing to a less prominent role of these pathways in determining breast cancer disease progression." (PMID 28916782, 2017). "The mechanism for human PVT1 function, as shown in breast cancer, involves PVT1 stabilization of the MYC protein." (PMID 28875933, 2017).
breast cancer (continued). "A pooled genomewide shRNA screen in mammary cancer cell lines identified BUD31, a gene involved in spliceosome catalytic activity, as a synthetic dose lethal partner of MYC amplification." (PMID 28097822, 2017). "Together, our data suggest that MYC is required for TIM-mediated CSC self-renewal and cell invasion in breast cancer." (PMID 28464854, 2017). "We evaluated EGFR, HER2, c-MYC, and MET gene status by determining the degree of amplification, GCN gain and the 2013 ASCO/CAP HER2 testing guideline criterion for breast cancer." (PMID 28764718, 2017). "Here, we used MCF7 cells as a model system to interrogate how MYC/RAS co-operativity contributes to metabolic flux and stemness in breast cancer cells." (PMID 29080556, 2017). "Based on a recent study that identified the spliceosome as a therapeutic vulnerability in MYC-driven breast cancers, we evaluated the efficacy of a spliceosome inhibitor in SCLC cell lines and analyzed the correlation with MYC status." (PMID 28192473, 2017). "(2011) reported c‐MYC‐mediated BRCA1 promoter activation, an essential component of HRR in breast cancer, which influenced I‐SceI‐induced HRR." (PMID 28173629, 2017). "A previous report indicated combined activation of TERT expression by MYC and ETS2 at this location in breast cancer cells." (PMID 28978027, 2017). "We evaluated the applicability of the ASCO/CAP HER2 guideline criterion for breast cancer to assess the EGFR, HER2, c-MYC, and MET gene status." (PMID 28764718, 2017). "A mammosphere formation assay suggested the number and size of the mammosphere formationby breast cancer cells with HN1 overexpression and inhibition of MYC were significantly reduced." (PMID 28490334, 2017). "Taken together, our data suggest that MYC is the critical downstream effector in TIM-mediated stem cell self-renewal, cell migration and invasion in breast cancer." (PMID 28464854, 2017). "A transwell assay showed that invasion was significantly inhibited in breast cancer cells that overexpressed HN1 and inhibition of MYC." (PMID 28490334, 2017). "In breast cancer models, HOTAIR has been shown to promote metastasis through re-location of PRC2, and PVT1 expression correlates with MYC protein levels and influences its stability." (PMID 28875933, 2017). "We did not observe a significant association of MYC copy number gains with immune estimates in melanoma in our models that include purity estimates as a covariate, but did observe associations of small effect size in head/neck, stomach, and the Luminal B subtype (LumB) of breast cancer." (PMID 28749946, 2017). "In breast cancer cell lines inhibition of VEGFR and PI3K signaling by the multi-kinase inhibitor Sorafenib leads to a reduction of MYC activity." (PMID 28159923, 2017). "For this purpose, we considered breast cancers, where amplifications of ERBB2 (Chromosome 17), CCND1 (Chromosome 11) and MYC (Chromosome 8) oncogenes are frequently observed (∼15%, 11% and 38%, respectively in the TCGA cohort)." (PMID 29069713, 2017). "EPO increases MYC expression in erythroid progenitor cells and we found that EPO increases MYC expression in both breast cancer cell lines." (PMID 28418910, 2017). "We demonstrated that the drivers showed significant attributes of cancer genes, and significantly overlapped with known cancer genes, including MYC, CCND1 and ERBB2 in breast cancer, and the lncRNA PVT1 in multiple cancer types." (PMID 28719033, 2017). "In the future, we will examine additional genes such as MYC, KRAS, and ERBB2 in breast cancer and other cancers." (PMID 27846853, 2016). "For example, the MYC, miR-98 and LINC00665 motif was dysregulated only in breast cancer, while the MEF2C, miR-145 and JPX motif was dysregulated only in bladder cancer." (PMID 27322142, 2016).
breast cancer (continued). "These subtype-specific breast cancer metabolism signatures contained a common set of five genes (SQLE, PYCRL, TSTA3, CYC1 and SLC39A4) which were co-amplified with MYC on chromosome 8q24 and showed a positive correlation with hypoxia." (PMID 27358048, 2016). "To further substantiate the positive regulatory role of nuclear AURKA and hnRNP K in MYC expression and promotion of BCSC phenotype, we isolated primary cells from human breast cancer tissues." (PMID 26782714, 2016). "While ADA3 overexpression correlated with c-MYC overexpression, survival analyses showed that low ADA3 expression serves as an independent marker for poor survival in ER+ breast cancer patients." (PMID 27852327, 2016). "Analyses of a well characterized cohort of breast cancer tissue samples for nuclear ADA3 and c-MYC expression helped categorize breast cancers into four groups; ADA3 Low/c-MYCLow, ADA3High/c-MYCLow, ADA3Low/c-MYCHigh and ADA3High/c-MYCHigh group of patients." (PMID 27852327, 2016). "For example, MYC and MYCN genes regulate the expression of miR-9 in breast cancer, and DNA methylation influences miR-9 expression in colorectal cancer." (PMID 27917340, 2016). "At the gene levels, genes with recurrent amplifications in breast cancer showed different degrees of concordance: 100% for ERBB2 and FGFR1, 96% for CCND1, but 88% for MYC, suggesting possible differences for driver genes." (PMID 27028851, 2016). "For example, an L-FFL motif comprised of the lncRNA H19, the TF MYC and the miRNA miR-29c, and an ceRNA motif comprised of the mRNA COL3A1, the lncRNA H19 and the miRNA miR-29c, were both dysregulated in breast cancer." (PMID 27322142, 2016). "We then focused the comparison of CNAs on known driver oncogenes located within regions frequently amplified in breast cancer: ERBB2 (17q12), CCND1 (11q13.3), FGFR1 (8p11.23), MYC (8q24), and PAK1 (11q14.1)." (PMID 27028851, 2016). "In both breast cancer and AML cells, it has been reported that PVT1 protects MYC from phosphorylation by the direct interaction with MYC, stabilizing and enhancing MYC." (PMID 27999732, 2015). "The other 2 lncRNAs, MYCLo-5 and -6 were also induced by MYC repression in various cancer types such as CRC (HCT116, RKO and HT29), lung cancer (A549), prostate cancer (PC3), breast cancer (MCF7 and SKBR3) and hepatocellular carcinoma (SK-HEP-1 and HepG2)." (PMID 26003165, 2015). "Previously, it was reported that c-MYC, an estrogen-regulated gene in ER+ breast cancer cells, was also able to bind to and activate the transcription of the H19 gene, which indicates that estrogen signaling might in fact indirectly regulate the expression of H19 through the activation of c-MYC." (PMID 25944846, 2015). "Another interesting study found that VEGFR-2 recruits JAK2/STAT3 to activate embryonic stem cell transcription factors MYC and SOX2 in breast cancer CSCs." (PMID 26500608, 2015). "c-MYC copy number was assessed by FISH and was successful for 20 of 33 (61%) sporadic breast cancer samples and 9 of 18 (50%) radiogenic breast cancer samples." (PMID 25531321, 2015). "The results in breast cancer lines show that neratinib and GSK-1070916 can be a targeted combination in the context of MYC amplification." (PMID 26018524, 2015). "Remarkably the combined analysis of MYC, HER2, CCND1 and PTEN aberrations suggested that aberrations of multiple PTEN/AKT pathway genes have a strong additive effect on breast cancer prognosis." (PMID 26672755, 2015). "With regard to MYC, these results both validate CIP2A's role in regulating MYC-mediated gene expression and provide a plausible novel explanation for the high MYC activity in basal-like and HER2+ breast cancers." (PMID 25015035, 2014).
breast cancer (continued). "In summary, when glutamine and glucose are abundant, MYC promotes their uptake and uniquely controls GLS and GLUL expression in antiestrogen resistant breast cancer cells." (PMID 25339305, 2014). "In support of this, we observed that c-MYC and c-SRC, proteins elevated in breast cancers, were also elevated following TFPI1 expression." (PMID 24489651, 2014). "All these results demonstrate that MYC and E2F regulates the expression of EXO1 in breast cancer cells." (PMID 24147022, 2013). "Elevated NFkB binding activity has been observed in both primary human breast cancer tissues and breast cancer cell lines, and contributes to the activation of CYCLIN D1, c-MYC, and MUC1." (PMID 24243820, 2013). "Several studies have reinforced the significance of c-MYC as an ERBB2 effector and the functional role that the two genes play in breast cancer progression." (PMID 23421821, 2013). "It regulates numerous oncogenes, like RAS, MYC and HMGA2, it was found to be down-modulated in different cancer types and restoration in breast cancer inhibited tumor growth, validating its role as tumor-suppressor." (PMID 24284394, 2013). "When we tested a larger panel of 21 breast cancer lines, however, we confirmed the strong correlation between decrease in viability after knockdown of ATAD2 or MYC (R2 = 0.61, p<0.001)." (PMID 23393560, 2013). "In unsupervised hierarchical clustering a distinctive group of male breast cancer with poor prognosis (p = 0.009; hazard ratio 3.4) was identified, characterized by frequent CCND1, MTDH, CDC6, ADAM9, TRAF4 and MYC copy number gain." (PMID 22527098, 2012). "The common hub genes between the SRF 50 and Parker breast cancer gene lists were ESR1, MYC, NFkB and ERK1/2." (PMID 22616791, 2012). "We found that siRNA-targeted depletion of a cohesin subunit, RAD21, decreased MYC expression in ER-positive (MCF7 and T47D) and ER-negative (MDA-MB-231) breast cancer cell lines." (PMID 23145106, 2012). "Genes of known importance in breast cancer and estrogen signaling, including ERBB2, PGR, MYC, CLU, and NCOA2, were among those identified as Sin3A-responsive." (PMID 20920219, 2010). "In ER+ breast cancer, we find that simultaneous high MYC and RAS activity confers significantly worse prognosis than either high MYC or high RAS activity alone." (PMID 21050467, 2010). "Prominent among these were sets of genes induced by MYC in human primary mammary epithelial cell cultures (HMECs) and in MCF-7 breast cancer cells (both with FDR<0.0001)." (PMID 19270750, 2009). "Expression of the c-Myc protein or the c-MYC gene is increased in a variety of human cancers, including over 80% of mammary cancers, 70% of colon cancers and 50% of hepatocellular carcinomas." (PMID 18940011, 2008). "We have created a new model for ERα-positive breast cancer by transduction of normal HMECs with lentiviruses expressing ERα, BMI1, MYC and TERT." (PMID 17573968, 2007). "Determination of coamplification rates of major oncogenes such as MYC and CCND1 in breast carcinomas should provide important information regarding prognosis." (PMID 17262082, 2007). "We therefore documented the neoplastic nature of the cells by assessing the gene status of other frequently amplified oncogenes in breast carcinomas, especially CCND1 (cyclinD1) and MYC." (PMID 17262082, 2007). "The FUBP protein exerts regulatory control over EMT during the metastasis of PC cells via the transforming growth factor beta (TGF-β)/Smad signaling pathway; additionally, it has been shown to activate the c-MYC upstream element (FUSE) to regulate c-MYC transcription in lung and breast cancers." (PMID 40265011, 2025). "Genes MYC and AR are known to be over-expressed in specific breast cancer subtypes, but this pattern was not proven for the entire, much more heterogeneous, cohort of TCGA breast cancer samples." (PMID 40724805, 2025).